CD14 (CD14 molecule)
Diseases named in the same sentence as CD14 in open-access papers (continued):
Sharing a sentence is not in itself a finding about the gene and the disease.
leprosy (6 papers, 2016 to 2023). Leprosy is a chronic infectious disease affecting primarily the skin and peripheral nervous system. "There was a higher expression of PDL-1 on CD14+ monocytes, CD11c+ dendritic cells and CD19+ B cells, suggesting that these cells play a role in the impairment of the innate immune system in leprosy." (PMID 37153623, 2023). "CD14+CD209+CD163+ triple positive cells are also described in the human dermis, in a murine leprosy model, and in the decidua of early human pregnancy." (PMID 36291154, 2022). "The presence of M-MDSC (CD14+CD11b+MHCII±) and G-MDSC (CD15+CD11b+MHCll±) in skin lesions of leprosy patients were evaluated." (PMID 34627197, 2021). "Even the ligand PDL-1 was higher on CD14+ monocytes and CD19+ B cells suggesting their role in host immune impairment in leprosy." (PMID 26751584, 2016).
liver inflammation (6 papers, 2013 to 2024). "Moreover, a human study also showed that serum-soluble CD14 levels were significantly correlated with liver inflammation and fibrosis in patients with NAFLD." (PMID 39200311, 2024). "Similarly, previous report showed that circulating microparticles from CD14 positive cells were correlated with severity of liver inflammation in patients with NAFLD." (PMID 23762319, 2013). "Mechanisms by which CD14+CD16+ monocytes contribute to HIV-NCI have not been characterized in a study population of PWH on ART without contribution from confounders that affect cognition (e.g., substance use, hepatitis C virus coinfection)." (PMID 39253970, 2024).
lung adenocarcinoma (6 papers, 2015 to 2026). A carcinoma that arises from the lung and is characterized by the presence of malignant glandular epithelial cells. "In conclusion, we demonstrated that the degree of CD14+ cell TME infiltration was associated with survival in 189 patients with resected lung adenocarcinoma." (PMID 36139660, 2022). "Overall, our data support the hypothesis that the increasing levels of CD14+ cell infiltration in early-stage lung adenocarcinoma result in a tumor survival benefit that associates with poor patient outcomes." (PMID 36139660, 2022). "Immunohistochemistry for CD14 was performed on 189 specimens from patients with lung adenocarcinoma who underwent curative intent surgery." (PMID 36139660, 2022). "In the present study, we used CD14-positive cells isolated from the peripheral blood of patients with advanced lung adenocarcinoma." (PMID 35589776, 2022). "While collectively, these studies suggest that CD14+ cells within the TME of patients with lung adenocarcinoma may contribute to poor outcomes, little is known about their prognostic impact." (PMID 36139660, 2022). "In this study, we investigated the presence of CD14+ cells within the lung adenocarcinoma TME through immunohistochemistry and found that higher levels of CD14+ cells were correlated with shorter patient survival." (PMID 36139660, 2022).
lung disease (6 papers, 2011 to 2024). "In contrast, while the CD45+Pro-Col-Iα1+ cells obtained from obtained from patients with lung disease also expressed high levels of CD14, many of these cells also expressed CD34." (PMID 21586112, 2011). "These include CD14, CD40, and CD80, which are surface receptors that trigger NF-κB activation, and IL-8, IL-6, and RANTES that are NF-κB-responsive cytokines with major roles in the pathogenesis of CF lung disease." (PMID 32528461, 2020). "Expression of CD11c and CD14 has been shown to identify AM phenotypes with changes in expression occurring during the fibrotic stage of lung disease Here, no significant changes in AM expression of CD11c or CD14 over the time period studied were observed." (PMID 31333668, 2019).
ovarian tumor (6 papers, 2013 to 2025). "CREB is widely recognized to induce IL-10 expression, which is elevated in ovarian tumor ascites and is a mechanism of suppression by ovarian tumor-associated CD14+ cells." (PMID 26343197, 2015). "Ovarian tumor-associated CD14+ myeloid cells are chemo-attractive for CD4+ T cells, and are strongly immunosuppressive for dendritic cell-stimulated tumor antigen-specific T cell responses." (PMID 26343197, 2015). "The PI3K/AKT/CREB axis may also be a predominant signaling pathway driving the M2 phenotype of ovarian tumor-associated CD14+ cells." (PMID 26343197, 2015). "This expanded population of CD14+CD16− myeloid cells, likely representing precursors to tumor‐associated macrophages, can be recruited to ovarian tumors, resulting in enhanced immunosuppression." (PMID 39887612, 2025). "It will be important to determine whether STAT3 phosphorylation correlates with PD-L1 expression, and further determine whether treatment of ovarian tumor ascites CD14+ cells with small molecule inhibitors of STAT3 leads to reduced PD-L1 expression." (PMID 26343197, 2015). "Versican V1 produced by ovarian tumor cell leads to activation of TLR2 and its coreceptors TLR6 and CD14 in macrophages." (PMID 23424670, 2013). "We evaluated numerous cell types, including IL-2 expanded T cells, CD14+ derived monocytes, but chose adipose tissue derived MSC due to their ability to be infected by MV and co-localization with ovarian tumors." (PMID 23347343, 2013).
parasitemia (6 papers, 2009 to 2025). "Together, the results revealed a dramatic expansion of CD14+CD16− monocytes after parasite infection in vitro with a concomitant increase of CD64 expression but a strong decrease of CCR2." (PMID 31316920, 2019). "TNF, a pro-inflammatory cytokine produced primarily by γδ T cells and CD14+ monocytes during malaria infection in humans, plays a key role in controlling parasitemia, but can cause damage if not tightly regulated." (PMID 41279035, 2025). "Importantly, resistance of CD14-KO mice to ECM was parasitemia dependent; the few CD14-KO mice that developed ECM had a parasite burden comparable to WT mice." (PMID 19710907, 2009). "However, in our present study increased expression of CD14 gene in infected sheep may be due to its action as a pattern recognition receptor in parasitic infection." (PMID 34335567, 2021).
peripheral artery disease (6 papers, 2016 to 2025). "Elevated levels of CD16+ subsets have been observed in patients with AAA, and a recent study showed that only intermediate monocytes (CD14++CD16+) were elevated in AAA patients compared to healthy individuals and peripheral artery disease (PAD) patients." (PMID 40969758, 2025). "The proportion of classical monocytes expressing high levels of CD14 and CD64 may increase in patients with diabetic peripheral arterial disease." (PMID 40469434, 2025).
systemic inflammatory response syndrome (6 papers, 2009 to 2026). SIRS is a serious condition related to systemic inflammation, organ dysfunction, and organ failure. "LPS combined with CD14 would stimulate the release of inflammatory mediators from monocytes and endothelial cells, and finally cause systemic inflammatory response syndrome." (PMID 28450824, 2017). "Sutherland provided data on CD14 and TLR 2 in patients with systemic inflammatory response syndrome." (PMID 19809507, 2009). "Trauma and surgical stress responses are associated with significantly elevated numbers of suppressive CD14 + HLA-DRlow/-monocytes and CD16BRIGHT CD62LDIM neutrophils, leading to activation of inflammatory factors such as interleukin 6 and inducing a systemic inflammatory response syndrome." (PMID 37140597, 2023).
anemia (5 papers, 2020 to 2026). A reduction in the number of red blood cells, the amount of hemoglobin, and/or the volume of packed red blood cells. "Human immunodeficiency virus (HIV) or simian immunodeficiency virus (SIV) infection causes myelodysplasia, anemia, and accumulation of inflammatory monocytes (CD14+ CD16+) through largely unknown cellular and molecular pathways." (PMID 34106001, 2021). "Dogs with a low hematocrit (an indicator of anemia) had significantly more infected CD14+ monocytes in the skin and were more infectious to feeding sand flies than dogs without anemia." (PMID 39514579, 2024). "IMPORTANCE HIV-1 and SIV infection often lead to myelodysplasia, anemia, and accumulation of inflammatory monocytes (CD14+ CD16+), with the latter likely involved in neuroAIDS." (PMID 34106001, 2021). "Based on the relationship between bone marrow and hematologic/erythroid abnormalities in CanL, we investigated the relationship between the number of infected dermal CD14+ monocytes and hematocrit (HCT), an indicator of anemia on routinely run bloodwork." (PMID 39514579, 2024). "In addition to inhibiting erythropoiesis and creating anemia, bone marrow parasitism could promote the accumulation of infected and uninfected CD14+ monocytes in the skin by facilitating entry of parasitized cells into circulation and dispersal to peripheral tissues." (PMID 39514579, 2024). "LeishVet II dogs also had similar fold changes in infected CD14+ monocytes–a 2.25-fold increase between dogs with no anemia vs mild anemia, and a 3.45 fold increase between dogs with no anemia vs moderate/severe anemia." (PMID 39514579, 2024). "However, when predicted probabilities of HCT based on infected CD14+ monocyte counts were calculated, no anemia (HCT > 37%) had the lowest probability, which consistently decreased as the average number of infected CD14+ monocytes increased." (PMID 39514579, 2024).
ankylosing spondylitis (5 papers, 2005 to 2026). An autoimmune chronic inflammatory disorder characterized by inflammation in the vertebral joints of the spine and sacroiliac joints. "In our study, the results of flow cytometry reveal that the mean fluorescence intensity (MFI) of CD147 expression on CD14+ monocytes of peripheral blood from RA patients was higher than that in normal control and ankylosing spondylitis (AS) patients." (PMID 16207318, 2005).
Anxiety (5 papers, 2014 to 2023). Intense feelings of nervousness, tension, or panic often arise in response to interpersonal stresses. "High levels of stress were associated with elevations of soluble CD14, lipopolysaccharide binding protein (LBP), and tumor necrosis factor–α, while anxiety was associated with elevated concentrations of C-reactive protein (CRP) in otherwise healthy pregnancies." (PMID 33301421, 2021). "Furthermore, among the highly myopic patients, those with anxiety (total anxiety score ≥ 7) also had higher ratios of monocytes (7.77 ± 2.15% vs 4.16 ± 1.10%, respectively, P = 0.0032) and CD14+/CD68+ monocytes (7.71 ± 2.12% vs 3.74% ± 1.65%, respectively, P = 0.0064) than those with no anxiety." (PMID 37699875, 2023).
bipolar disorder (5 papers, 2019 to 2023). A disorder of the brain that causes unusual shifts in mood, energy, activity levels and the ability to carry out day-to-day tasks. "Bipolar disorder risk SNP rs7618915, an upstream SNP, is annotated by the important annotations including Monocytes-CD14+ RO01746 Primary Cells, Brain Anterior Caudate and Primary B cells from peripheral blood, which contributes to its high prior probability." (PMID 36744920, 2023). "We also found increased CD163, CD14 and ICAM1 mRNAs in high compared to low inflammation bipolar disorder (39–104%, all post hocp ≤ 0.008)." (PMID 34911938, 2021).
brucellosis (5 papers, 2008 to 2024). Brucellosis is a bacterial infection that spreads from animals to people via unpasteurized dairy products or by exposure to contaminated animal products or infected animals. "Our further analysis confirmed that Mono_CD14 (classical monocytes) and Mono_MDSCs were the major contributors to the potential inflammatory storm present in acute brucellosis patients." (PMID 39135683, 2024). "In the present study, we found that the proportion of CD14++CD16− monocytes in patients with brucellosis was significantly higher than in HC, whereas the proportion of CD14+CD16+ monocytes was significantly lower." (PMID 28659924, 2017). "We have previously shown that heat-killed B. abortus (HKBA) can downregulate the PHA-induced increase of CD4+/CD25+ and CD14+/CD80+ cells of brucellosis patients." (PMID 19190764, 2008). "In agreement with our findings, the monocyte subpopulation in patients with brucellosis was also abnormal; what was different from our study was that the number of CD14++CD16− monocytes was significantly higher in patients with brucellosis than the numbers of other monocyte subsets." (PMID 33282751, 2020). "In summary, we found that Brucella infection led to an increase in the proportion of CD14++CD16− monocytes, a decrease in the proportion of CD14+CD16+ monocytes, and increased expression of the autophagy-related protein LC3B in CD14++CD16− monocytes obtained from brucellosis patients." (PMID 28659924, 2017). "Specifically, inchronic brucellosis patients, high percentage of CD14+/CD80+ monocytes in PHAand PHA plus E. coli LPS cultures might compensate for an ineffectualCD4+ T-cell response characterizing these form of disease." (PMID 19190764, 2008). "Clinical monocytes (Mono_CD14) are the predominant subtype of monocytes, distinct UMAP projection patterns of this cluster between brucellosis patients and healthy controls suggest perturbed transcriptome features, especially for those in the acute stage." (PMID 39135683, 2024). "We also found that the expression of TLR-2 (CD282) and TLR-4 (CD284) on all three monocyte subsets, particularly on the CD14++CD16− monocyte subset, increased in brucellosis patients compared with HC." (PMID 28659924, 2017). "Regarding the frequency of CD14+monocytes expressing CD80 costimulation molecule, a significant increase wasfound in both of brucellosis groups in comparison to “cured” (P = .002 and .001,resp)." (PMID 19190764, 2008). "Classical monocytes (Mono_CD14), which are the predominant myeloid cell type in PBMCs, are affected by brucellosis as indicated by UMAP projection patterns of this cluster between brucellosis and controls as well as an enrichment in acute patients." (PMID 39135683, 2024). "E.coli addition in PHA cultures did not further enhance the increase in thepercentage of CD14+/CD80+ monocytes in both groups of brucellosis patients." (PMID 19190764, 2008). "Our results indicated that infection with Brucella leads to an increase in CD14++CD16− monocytes and a decrease in CD14+CD16+ monocytes, as well as an increase in the expression of the autophagy-related protein LC3B in all monocyte subsets obtained from brucellosis patients." (PMID 28659924, 2017).
cholestasis (5 papers, 2009 to 2022). Impairment of the bile flow caused by obstruction within the liver, or outside the liver in the bile duct system. "Consistent with our observations, a previous study revealed that hepatic CD14 upregulation led to increased endotoxin sensitivity and host proinflammatory reactions, causing organ failure and mortality in a rat model of cholestasis." (PMID 23817990, 2013). "CD14 production by hepatocytes and bile duct epithelial cells during cholestasis and the relationship with CD14 expressed on the Kupffer cells and sinusoidal endothelial cells is still not clear." (PMID 22511970, 2012). "We focused on the ability of LPS-elicited CD14 fluctuations in hepatocytes and HSCs during cholestasis to affect LPS reactivity and clearance." (PMID 22511970, 2012). "In conclusion, cholestasis and LPS stimulation were here found to upregulate hepatic CD14 expression, which may have led to increased endotoxin sensitivity and host proinflammatory reactions, causing organ failure and death in BDL rats." (PMID 22511970, 2012). "The aims of this study are to test the hypothesis that CD14 is upregulated by LPS and investigate the pathophysiological role of CD14 production during cholestasis." (PMID 22511970, 2012). "The aims of this study are to test the hypothesis that CD14 is upregulated by LPS for endotoxin clearance and to investigate the pathophysiological mechanisms and roles of CD14 production during cholestasis." (PMID 22511970, 2012). "However the endotoxin levels in liver tissues were still high due to cholestasis, and CD14 production was increased again at 7 days after ligation." (PMID 21172039, 2010). "During cholestasis, the accumulation of endotoxin may induce hepatocyte injury and impair CD14 synthesis during late-stage BA." (PMID 21172039, 2010). "It is suspected that high expression of CD14 in Kupffer cells and sinusoidal endothelial cells may imply a response of these cells to cholestatic liver injury or to increased endotoxin as a result of cholestasis." (PMID 21172039, 2010). "We evaluate the in vitro effect of LPS on TLR4, CD14, and MD2 expression in hepatocytes and a hepatic stellate cell line and on endotoxin sensitivity during cholestasis by BDL animals." (PMID 22511970, 2012). "In summary, our in vitro and in vivo data indicate an enhanced sensitivity of hepatocytes to endotoxin with increased CD14 and MD2 expression during cholestasis." (PMID 22511970, 2012). "Therefore, we cannot rule out the possibility that CD14 production by hepatocytes and bile duct epithelial cells during cholestasis and its subsequent transportation to the Kupffer cells and sinusoidal endothelial cells produces an unknown downstream effect." (PMID 21172039, 2010).
cognitive decline (5 papers, 2019 to 2025). "In addition, we found that immune cell subsets were uniquely, but to a lesser extent, associated with cognitive decline, as measured by different neuropsychological tests, per AD stage (for example, CD14+ monocytes ~ RAVLT immediate recall, rMCI = -0.64, and rDem = 0.45)." (PMID 38658964, 2024). "Deletion or inhibition of the CD14-TLR receptor complex will impair fibrillary Aβ1-42 uptake in human monocytes and delay cognitive decline in a mouse model of AD35,36." (PMID 33293506, 2020).
epilepsy (5 papers, 2018 to 2026). A brain disorder characterized by episodes of abnormally increased neuronal discharge resulting in transient episodes of sensory or motor neurological dysfunction, or psychic dysfunction. "Although Iba1+ CD14+ or CD163+ cells were identified in epilepsy tissue, where present, they were predominantly associated with blood vessels, indicative of perivascular macrophage expression." (PMID 34286275, 2021). "In parallel, both microglia and circulating CD14+ monocytes exhibit signs of immune activation in epilepsy, suggesting myeloid-driven inflammatory rewiring that extends beyond the brain." (PMID 41757101, 2026). "CD14 staining was observed variably throughout low-grade, meningioma, and grade IV tumors, but scarcely in epilepsy tissue (Figure 3A1–H1)." (PMID 34286275, 2021). "Colabeling of Iba1 with proposed TAM-specific markers CD14 and CD163 revealed a subset of both Iba1+ CD14+ or CD163+ and Iba1+ CD14− or CD163− cells in both tumor and epilepsy tissue." (PMID 34286275, 2021). "Comparison of the mean single-cell CD14 or CD163 average intensity per case revealed an upregulation of both CD14 and CD163 in gated microglia from tumor tissue when compared to epilepsy tissue, showing microglia have the capacity to upregulate these markers in the context of tumors." (PMID 34286275, 2021). "A recent subset of monocytes, CD14− and CD16− monocytes, characterized by the absence of their surface markers CD14 and CD16, is gaining increased attention for their role in neuroinflammatory states associated with chronic conditions such as epilepsy and neurodegenerative diseases." (PMID 40894200, 2025). "Interestingly, CD14 immunoreactivity was not restricted to TAMs and was observed in tumor microglial populations, with a significant upregulation when compared to epilepsy microglia." (PMID 34286275, 2021).